EGFR (epidermal growth factor receptor)
Diseases named in the same sentence as EGFR in open-access papers (continued):
Sharing a sentence is not in itself a finding about the gene and the disease.
breast carcinoma (continued). "Similar to our study, another investigation in breast cancer cell lines showed that DA induces cell cycle arrest, represses cell migration and invasion, and reduces colony formation via EGFR signaling." (PMID 38431613, 2024). "In this study, the core components regulate five key targets: MAPK1, LCK, JAK2, HSP90AA1, and EGFR, all of which are uniquely expressed in breast cancer." (PMID 39867914, 2024). "CK5/6 and EGFR expression were accepted as biomarkers for classification of Basal-like breast cancer within the TNBC subtype." (PMID 38576013, 2024). "For example, overexpression of EGFR has been documented as a predictive factor influencing the response to trastuzumab in HER2+ breast cancer." (PMID 39668367, 2024). "To note, the protein–protein interaction network of PIK3R1, IL1R1, MMP11, GOLM1, and VAV3 altogether connected by EGFR merits further work to understand the mechanism and develop an ideal treatment strategy for invasive small tumor-size breast cancers." (PMID 39190284, 2024). "This particular study concentrated on the visualization of liver metastasis by labeling MDA-MB231 breast cancer cells with QDs-EGFR antibody." (PMID 38730959, 2024). "Downregulation of metalloprotease-disintegrin ADAM12 reduces cell migration, invasion and anoikis-resistance in claudin-low breast cancer cells by suppressing the activation of EGFR signaling pathway." (PMID 39238997, 2024). "A frequently cited success example in this regard is the study of the human epidermal growth factor receptor (HER)‐2 gene in breast cancer." (PMID 37211956, 2023). "Watt and Kumar showed the co-expression of all SSTR subtypes with epidermal growth factor receptor subtypes (ErbBs) in human breast cancer cell lines." (PMID 38203605, 2023). "Other types of EGFR intragenic fusion are also extremely rare, where only one breast cancer case (<0.1%) had reported EGFR intragenic fusion with an out-of-frame deletion of six exons." (PMID 38201434, 2023). "Fulvestrant (F), lapatinib (L), and paclitaxel (P) are hydrophobic, anticancer drugs used in the treatment of estrogen receptor (ER) and epidermal growth factor receptor (EGFR)-positive breast cancer." (PMID 37687164, 2023). "Together, these results demonstrated that PELI1 knockdown synergized with EGFR inhibitor and that combined therapy showed superior activity against breast cancer metastasis." (PMID 36841821, 2023). "The EGFR inhibitor gefitinib inhibits breast cancer cell proliferation and sensitizes cells to carboplatin and docetaxel." (PMID 37670360, 2023). "Successful in vivo targeting has been shown with EV display of DNA aptamer (AS1411) that binds nucleolin for breast cancer targeting, RNA aptamer that binds EGFR, as well as RNA aptamer binding prostate-specific membrane." (PMID 39697988, 2023). "EGFR and related signaling molecules are currently important targets for the treatment of breast cancer, leading to improved patient survival." (PMID 36810560, 2023). "It suppresses the growth and invasion of breast cancer cells by downregulating the EGFR/MEK/ERK pathway." (PMID 37687271, 2023). "EGFR recycling is also regulated by ISGylation leading to the more aggressive tumor behaviors observed in breast cancer." (PMID 36841821, 2023). "The AMPK activation regulates HER2 and the epidermal growth factor receptor (EGFR) in HER2-amplified breast cancer cells, leads to myocardial protection and attenuates TIC." (PMID 38068999, 2023). "Singh groups reported a novel hybrid analogue of monastrol-1,3,5-triazine 10 as an effective anti-breast cancer agent in 2017, which showed excellent EGFR-TK enzyme inhibitory activity (96.3% at 10 μM)." (PMID 37298753, 2023). "A higher expression of PAK4 promoted proliferation and invasiveness through activation of the PI3K/AKT pathway in breast cancer cells and through c-Src and the EGFR pathway in ovarian cancer cells." (PMID 36980457, 2023).
breast carcinoma (continued). "GSEA analysis in an ER+/HER2- breast cancer dataset revealed significant enrichment of genes upregulated upon EGFR overexpression among high PDE4D-expressing patients’ tumors." (PMID 37914699, 2023). "TFAP2C directly interacts with the EGFR gene to promote its expression, resulting in luminal breast cancer cell proliferation and an improved therapeutic effect of TKI (Vandetanib)." (PMID 37291585, 2023). "Reciprocally, antibody-mediated inhibition of integrin β1 decreased the total and activated EGFR protein in EGFR overexpressing breast cancer cells." (PMID 37084657, 2023). "Though these results have yet to be validated in clinical trials, inhibition of EGFR in breast cancer was tested clinically due to evidence of EGFR overexpression in nearly half of TNBCs." (PMID 37163498, 2023). "The overexpression of EGFR occurs in all breast cancer subtypes but is more pronounced in invasive TNBC and IBC and is associated with tumor malignancy and poor prognosis." (PMID 36900322, 2023). "EVs tagged with the GE11 peptide to target breast cancer cells expressing EGFR were loaded with miRNA let-7a and significantly inhibited the proliferation of the cancer cells through a poorly understood pathway." (PMID 37894887, 2023). "Another lectin, Polygonatum odoratum, in addition to apoptosis, induces EGFR-dependent autophagy, where a decrease in the receptor phosphorylation and eventual degradation of total EGFR were observed in MCF-7 breast cancer cells." (PMID 37259433, 2023). "The activation of AMPK phosphorylation inhibits the activity of HER2 and EGFR, which further suppresses the growth of breast cancer." (PMID 36677797, 2023). "We further demonstrate in 3D cultures of patient-derived breast cancer explants that both basal TGFβ signaling and EGFR protein expression are inhibited by neutralizing antibodies or small-molecule inhibitors of hepsin." (PMID 37872868, 2023). "Trastuzumab resistance in HER2-positive breast cancer involves increased EGFR and IGF1R signals as well as dysregulation of the PTEN/PI3K/AKT/mTOR pathway." (PMID 38114573, 2023). "A previous study reported that IL-17E synergizes with EGF and confers EGFR-TKI resistance in breast cancer." (PMID 37444399, 2023). "Another investigation reported the effects of quercetin on inhibition of EMT, angiogenesis, and invasiveness through the epidermal growth factor receptor (EGFR)/VEGFR-2-mediated pathway in breast cancer." (PMID 36926328, 2023). "In this field, particular attention should be given to the generation of functional blocking molecules for MT4-MMP and exploring their combination with EGFR inhibitors in breast cancer." (PMID 37373092, 2023). "Another phase II multicenter trial in 31 patients with previously treated, advanced breast cancer with GEF resulted in complete inhibition of EGFR phosphorylation found in tumor biopsies." (PMID 38090376, 2023). "They pointed out that EVs expressing the surface protein EGFR were able to target and deliver therapeutic cargo to EGFR-positive cancer cells, reducing tumor growth in a mouse model of breast cancer." (PMID 37240353, 2023). "The EGFR or HER2 positive breast cancer cell lines MDA-MB-468 and SK-BR-3, respectively, were chosen as model systems to evaluate the role of sialic acid on tumor cell killing by PMN." (PMID 37346044, 2023). "This patient was diagnosed with multiple tumors over several decades, including bilateral breast cancer, malignant fibrous histocytoma, and an EGFR mutant lung adenocarcinoma." (PMID 37266578, 2023). "SP enhances malignancy and resistance in breast cancer cells by the transmodulation of epidermal growth factor receptor (EGFR) and epidermal growth factor receptor 2 (HER2)." (PMID 37958914, 2023). "Some of these oncogenes are paradigms of certain tumor types, as is the case of the amplification of EGFR/ErbB in breast cancer or MET overexpression in non-small cell lung cancer (NSCLC)." (PMID 36839989, 2023).
breast carcinoma (continued). "The co-inhibition of the PELI1-EGFR effectively repressed breast cancer metastasis and enhanced the sensitivity of EGFR-TKI." (PMID 36841821, 2023). "From 144 intersection targets of Ecliptae Herba and breast cancer, we then obtained the hub targets EGFR and TGFB1 of Ecliptae Herba for breast cancer treatment by constructing PPI network and MCODE function." (PMID 37832105, 2023). "The HB-EGF, a ligand for epidermal growth factor receptor (EGFR), has been shown to enhance breast cancer cells’ invasiveness to the brain." (PMID 37190188, 2023). "Breast cancer research has made significant advancements in the understanding of the epidermal growth factor (EGF) receptor (EGFR) gene family and EGF." (PMID 38090376, 2023). "Although various trials have been underway, the clinical benefit of EGFR inhibitor therapy in breast cancer patients is still a mystery." (PMID 38090376, 2023). "Previous studies on breast cancer indicate a correlation between EGFR signaling pathways and autophagy." (PMID 37575061, 2023). "The novel aspect of this study is that we examined a three-biomarker combination of CK5, CD117, and EGFR systematically and separately in the four established subgroups of breast cancer, focusing on TNBC." (PMID 36766486, 2023). "The mechanism of EGFR action on CHKα has been observed in breast cancer models, but EGFR also plays an important role in glioblastoma cancer." (PMID 37046844, 2023). "A cytotoxicity assay using a similar protocol conducted on MCF7, a breast cancer cell line known for low EGFR expression, showed enhanced cytotoxicity with the combination of NPe6 and light irradiation." (PMID 36655546, 2023). "Previous reports have shown that breast cancer patients with the expression of both EGFR and HER2 have a poorer prognosis than other groups using 825 tumor samples and frozen tumor sections from 670 primary breast cancer patients." (PMID 36674955, 2023). "To date, three HER2-targeted TKIs have been approved by the FDA for the treatment of HER2-positive breast cancer: a dual EGFR/HER2 inhibitor lapatinib, pan-HER inhibitor neratinib, and selective HER2 inhibitor tucatinib, which are not used in GC." (PMID 38114573, 2023). "STC1 upregulates the expression of S100A4 in breast cancer cells by promoting EGFR phosphorylation and ERK signaling." (PMID 37400459, 2023). "Specifically targeting HER2 surface receptors, an EGFR-class protein found in aggressive breast cancers, is an area that is being actively investigated with the aim of offering diagnostic and treatment solutions for certain malignancies." (PMID 37568284, 2023). "A recent study provides a more detailed possible mechanism through which the membrane protein sarcoglycan epsilon (SGCE) stabilizes EGFR for breast cancer stem cell (BCSC) maintenance by disrupting the interaction between EGFR and its E3 ligase c-Cbl." (PMID 36694209, 2023). "For the TN breast cancer patients, 67% of the patients were > 50 years old, only one was EGFR positive and presented lymphatic invasion." (PMID 36681070, 2023). "Dendrimer delivery of 5-aminolevulinic acid for protoporphyrin IX-based PDT has also been investigated in breast carcinoma cells, and targeting was achieved by attaching an EGFr-homing peptide to the dendrimer." (PMID 37048731, 2023). "Subclass of Verongimorpha: (+)-Aeroplysinin-1 (derived from Verongia aerophoba) reduced the EGF-stimulated proliferative capacity in MCF-7 breast cancer cells (0.5–0.25 μM) as well as EGFR endocytosis and EGFR kinase activity." (PMID 38132936, 2023). "In two stem-like breast cancer cell lines, induction of stemness can be performed by autophagy via the EGFR/Stat3 and TGFβ/Smad pathways in a murine model." (PMID 37190065, 2023). "Based on gene expression data, its new indication for luminal B pattern breast cancer has been discovered, and it is believed to inhibit breast cancer cell growth by acting on F10 and EGFR genes." (PMID 37765160, 2023).
breast carcinoma (continued). "Five molecular subtypes of breast cancer are defined: (i) luminal A, (ii) luminal B, (iii) epidermal growth factor receptor-positive (HER2+), (iv) triple-negative breast cancer (TNBC), and (v) seminormal." (PMID 36982173, 2023). "In HER2-positive breast cancer, lapatinib inhibits the activation of signalling pathways downstream of EGFR and HER2 including MAPK, PI3K-AKT and PLC-γ, leading to apoptosis, decreased cellular proliferation and cell cycle arrest." (PMID 37715141, 2023). "An additive or synergistic interaction between c-Met and EGFR has been found in multiple types of cancer cells, including breast cancer, hepatomas, and glioblastomas." (PMID 37611070, 2023). "We also examined the PELI1 and EGFR protein levels in breast cancer tissue microarray by IHC, and found a highly positive correlation." (PMID 36841821, 2023). "In this review, the role of EGFR in the development and pathogenesis of breast cancer and the pharmacokinetics and pharmacotherapy of GEF for the treatment of breast cancer have been elaborated." (PMID 38090376, 2023). "ERRFI1 is a negative regulator of the growth factor EGFR and has been identified in breast carcinoma as a gene altered by hypoxia." (PMID 37671061, 2023). "Pyrotinib (an irreversible pan‐ErbB small‐molecular tyrosine kinase inhibitor) was approved in human epidermal growth factor receptor 2 (HER2)‐positive breast cancer and showed great antitumor activity in preclinical studies of gastric cancer (GC)." (PMID 37081722, 2023). "GEMINI‐Exos effectively targets EGFR‐positive breast cancer cells, and its injection induces robust anticancer immunity and efficient tumor suppression in a mouse model of breast cancer." (PMID 37560754, 2023). "Other studies have shown that the re-expression of EGFR in MTLn3-paxillinS178A rescued spontaneous metastasis of breast cancer patients from breast to lung." (PMID 37623233, 2023). "The results showed that these nanoparticles potently enhanced the therapy efficacy to EGFR overexpressed breast cancer." (PMID 36794282, 2023). "Lapatinib impedes proliferation in breast cancer and inhibits the activation of EGFR, HER2, AKT, and ERK1/2 both in vitro and in vivo." (PMID 37190133, 2023). "Clinical trials for the treatment of breast cancer have shown promise for EGFR inhibitors such as erlotinib and gefitinib." (PMID 37711177, 2023). "Another adjuvant treatment that was under investigation involved OC combined with lapatinib, which is a well-known EGFR/HER-2 (Epidermal Growth Factor Receptor/Human Epidermal Growth Factor Receptor 2) inhibitor used for HER-2 amplified breast cancer." (PMID 38136231, 2023). "CHKα is also significant in EGFR-induced proliferation, as demonstrated by experiments on a breast cancer model." (PMID 37046844, 2023). "For example, mitochondrial translocation of EGFR occurs in breast cancer cells in response to EGF stimulation, which subsequently induces the phosphorylation of cytochrome c oxidase subunit II (Cox II) in the mitochondria and enhances cancer cell survival." (PMID 37461111, 2023). "The objective of this study was to determine the reason for the poor prognosis of breast cancer patients with the expression of both EGFR and HER2." (PMID 36674955, 2023). "EGF was shown to induce epithelial-mesenchymal transition (EMT) in EGFR-expressing human breast carcinoma cells." (PMID 36960065, 2023). "Epidermal growth factor receptor (EGFR), HER2, progesterone receptor (PR), Ki-67, PD-L1 and survivin are important gene markers associated with breast cancer." (PMID 37511584, 2023). "Alix-depleted basal-like breast cancer cells have also been shown to induce EGFR activity and EGFR-dependent PD-L1 presentation." (PMID 37371482, 2023). "Herein, we revealed a novel regulation mechanism by which PELI1 and EGFR cooperate to promote breast cancer metastasis." (PMID 36841821, 2023).
breast carcinoma (continued). "For example, the increase in SYNJ2 in breast cancer promotes the recycling of EGFR, stimulating cell movement and tumor formation." (PMID 36899380, 2023). "In previous reports, the co-expression of EGFR and HER2 in breast cancer was associated with decreased patient survival and increased metastasis." (PMID 36674955, 2023). "Our study not only uncovered the emerging roles of PELI1/EGFR interaction in the progression of breast cancer, but also provided an effective strategy for the inhibition of metastasis in breast cancer." (PMID 36841821, 2023). "Targeting EGFR is important for this study as dimeric pyridinium bromides show potent activity against breast cancer cells." (PMID 37880270, 2023). "SiNPs have been demonstrated cytotoxicity on breast cancer cells mediated through modulation of EGFR." (PMID 37893002, 2023). "Activation of the kisspeptin receptor KISS1R by the peptide hormone kisspeptin-10 (KP-10) stimulates invasion of breast carcinoma cells via transactivation of EGFR." (PMID 37071417, 2023). "Our findings suggest that J. humile suppresses breast cancer proliferation and induces cell cycle arrest and apoptosis partly by EGFR signaling pathway, highlighting J. humile as a potential therapeutic candidate against breast cancer." (PMID 37210476, 2023). "FAM38A is a transmembrane protein that acts as a proto-oncogene in breast cancer, downstream of the EGFR pathway." (PMID 37016335, 2023). "EGCG inhibits the expression of epidermal growth factor receptors (EGFR or ErbB) such as ErbB1 and ErbB2, which are overexpressed in breast cancer, especially in epidermoid carcinoma (A-431) and SK-BR3." (PMID 37445915, 2023). "We assessed miR-218 and EGFR expression in cell lines and publicly available primary breast cancer gene expression data." (PMID 37088795, 2023). "Silencing EGFR in SKBR3 (HER2+ breast cancer cell line) and MCF7 cells results in an elevated autophagy response." (PMID 37190065, 2023). "The 4-hydroxytamoxifen-resistant MCF-7 breast cancer cells can survive EGFR targeting by activating pro-survival autophagy." (PMID 37575061, 2023). "While low oxygen stabilizes HIFs and regulates a hypoxia induced response, receptor tyrosine kinases (RTKs) such as the epidermal growth factor (EGFR) family, which are commonly highly expressed in breast cancers can stabilize HIFs." (PMID 36910138, 2023). "A number of studies have reported that EGFR is more frequently overexpressed in TNBC compared with other subtypes of breast cancer." (PMID 37296801, 2023). "This is consistent with a previous study in breast cancer demonstrating that p-EGFR activates MUC1 by phosphorylating MUC1." (PMID 36810913, 2023). "Here we review the role of the EGF-SNX3-EGFR axis in breast cancers with an extended discussion on deregulated EGFR endocytosis in cancer." (PMID 37036745, 2023). "But their research demonstrated that PUFAs inhibited the epidermal growth factor receptor, which in turn decreased the growth of breast cancer." (PMID 37432206, 2023). "The SK-BR-3 cell line has amplified ERBb2 and high levels of EGFR, representing well-accepted model systems of ERBb2-positive breast cancer." (PMID 38090376, 2023). "Human epidermal growth factor receptor 2 (EGFR/HER2)‐positive breast cancer accounts for 15%–20% of all breast cancers and has a high invasive potential and poor outcome before the emergence of anti‐HER2 therapy." (PMID 35894763, 2023). "Patients with both EGFR-positive and HER2-positive breast cancer showed significantly poor disease-free survival (DFS, p = 0.0229) and overall survival (OS, p = 0.019) compared to patients with EGFR-positive breast cancer." (PMID 36674955, 2023). "Adding vasoactive intestinal peptide to breast cancer cells stimulates EGFR and HER2 tyrosine phosphorylation." (PMID 37508387, 2023). "Breast cancer typically has overexpressed and activated epidermal growth factor receptors (EGFR), which are receptor tyrosine kinases." (PMID 37711177, 2023).